ANGPTL3 (angiopoietin like 3)
Diseases named in the same sentence as ANGPTL3 in open-access papers (continued):
Sharing a sentence is not in itself a finding about the gene and the disease.
Hepatic steatosis (18 papers, 2014 to 2026). Steatosis is a term used to denote lipid accumulation within hepatocytes. "In participants with hepatic steatosis, repeat dosing at the same time point was associated with decreases in ANGPTL3 by 85%, TG by 44%, non–HDL-C by 37%, LDL-C by 35%, and apoB by 20%." (PMID 41561063, 2025). "It is difficult to explain these differences in the risk of developing hepatic steatosis between the various agents inhibiting ANGPTL3, particularly between the two that both decrease hepatic ANGPTL3 synthesis." (PMID 39751968, 2025). "In this study, we first analyze ANGPTL3 concentration in relation to body mass index (BMI), lipid profile, and markers of hepatic steatosis before and during weight loss." (PMID 29619113, 2018). "Altogether, ANGPTL3 may be involved in the pathogenesis of the metabolic syndrome and increase the risk of hepatic steatosis." (PMID 29619113, 2018). "In a phase I basket study, single- and repeat-dose cohorts in healthy adults and individuals with hepatic steatosis showed that, in healthy participants, by day 85 after a single injection ANGPTL3 decreased by 45–78%, TG by 34–54%, and non–HDL-C by 18–29%." (PMID 41561063, 2025). "Selective pharmacotherapeutic inhibition of ANGPTL3 synthesis in patients with T2D, hypertriglyceridemia, and hepatic steatosis significantly lowered triglyceride levels compared to placebo without improving glycemic parameters or hepatic fat content." (PMID 39409124, 2024). "First-in-human results from five cohorts of healthy volunteers and individuals with hepatic steatosis show that RNA interference treatment targeting ANGPTL3 was well tolerated and led to reduction in triglycerides and non-HDL cholesterol." (PMID 37626170, 2023). "The same results are found in advanced liver steatosis or steatohepatitis, where an increase in circulating levels of ANGPTL3 suggests a relation between liver inflammation and ANGPTL3 secretion." (PMID 33451033, 2021). "Our analysis also suggests an extended function of ANGPTL3 in the development of liver steatosis and shows a common genetic regulation for both ANGPTL3 and markers of liver function." (PMID 29619113, 2018). "We also examined the role of genetic variation in determining the level of circulating ANGPTL3 and the relation between the identified genetic markers and markers of hepatic steatosis." (PMID 29619113, 2018). "Our results suggest an extended function of ANGPTL3 in the inflammatory state of liver steatosis and toward liver metabolic processes." (PMID 29619113, 2018). "Due to the controversy of non-invasive biomarkers as measurement of liver diseases, additional studies should include actual liver biopsies to further evaluate the role of ANGPTL3 in liver steatosis." (PMID 29619113, 2018). "As a reaction to elevated plasma triglycerides (TGs) and liver steatosis, hepatic miR-27b was significantly increased, and the ANGPTL3 and GPAM protein, being targets of miR-27b, were significantly repressed." (PMID 25093715, 2014). "Pairing APOC3 or ANGPTL3 inhibitors with metabolic agents such as GLP-1/GIP receptor agonists may simultaneously address triglyceride burden, hepatic steatosis, pancreatitis risk, and cardiometabolic outcomes." (PMID 41300829, 2025). "Because ASO therapy targeting ANGPTL3 has been associated with increases in aminotransferases and liver fat17, we also report findings from a repeat-dose cohort evaluating ARO-ANG3 in participants with baseline hepatic steatosis." (PMID 37626170, 2023). "Hepatic steatosis has not been reported in carriers of ANGPTL3 loss-of-function variants, and animal studies support reduction of liver fat with ANGPTL3 inhibition." (PMID 37626170, 2023). "This study demonstrates that ANGPTL3, in addition to controlling lipid metabolism, also plays a role in fructose metabolism, which may have consequences for the development and progression of fatty liver disease." (PMID 40638391, 2025).
Hepatic steatosis (continued). "This review explores current and emerging TG-lowering therapies, including fibrates, omega-3 fatty acids, pemafibrate, and novel agents such as pegozafermin (an FGF21 analog), and APOC3 and angiopoietin-like protein 3 (ANGPTL3) inhibitors, in the context of hepatic steatosis and MASLD." (PMID 42206171, 2026). "In summary, regardless of study population (HPs or participants with hepatic steatosis), repeat dosing of ARO-ANG3 consistently reduced ANGPTL3 by approximately 80–90%." (PMID 37626170, 2023).
hepatoma (15 papers, 2014 to 2025). "Elevations of ANGPTL3 levels were reported in hepatocellular carcinoma and high‐grade serous ovarian cancer." (PMID 39888285, 2025). "In the first series of experiments, we explored the effect of ANGPTL3 gene silencing on lipid accumulation in human hepatoma cell line Huh7." (PMID 38612519, 2024). "It has been shown that ANGPTL3 exhibited potential oncogenic effects in oral cancer, hepatocellular carcinoma, as evidenced by the high intracellular expression of ANGPTL3 that successfully increased the tumorigenicity and invasiveness of the target cells." (PMID 37344779, 2023). "They observed that downregulation of ANGPTL3 inhibited cell proliferation and decreased invasion of hepatocellular carcinoma cells." (PMID 34484467, 2021). "Unpublished observations from our laboratory suggested a profound TGF-β-mediated decrease in ANGPTL-3 mRNA in hepatoma cells." (PMID 34360721, 2021). "Plasma concentrations of ANGPTL-3 were higher in patients with hepatocellular carcinoma and those with chronic hepatitis as compared with patients in the control group." (PMID 31741709, 2019). "On the other hand, in human hepatoma cells, Angptl3 silencing and deletion reduced apoB secretion and increased LDL/VLDL uptake." (PMID 29752428, 2019). "In rat and human hepatoma cells, the amount of Angptl3 mRNA and secreted ANGPTL3 protein decreased in a dose dependent fashion in the presence of insulin." (PMID 29752428, 2019). "Consistent with previous reports, western blot experiments illustrated that insulin decreased ANGPTL3 production in human hepatoma HepG2 cells." (PMID 27620179, 2016). "Yu and his group reported that ANGPTL3 was overexpressed in hepatocellular carcinoma." (PMID 34484467, 2021). "Silencing of ANGPTL3 in mouse models and in human hepatoma cells result in reduced output and increased uptake of Apo B-containing lipoproteins, thereby contributing to low LDL-CHOL observed in mice and humans with genetic ANGPTL3 deficiency." (PMID 33584351, 2021). "miR-27b was determined to target several lipid-associated genes in human hepatoma cell lines, for example heparan sulfate N-deacetylase/N-sulfotransferase 1 (NDST1), angiopoietin-like 3 (ANGPTL3), peroxisome proliferator-activated receptor γ (PPARG) and glycerol-3-phosphate acyltransferase 1 (GPAM)." (PMID 25093715, 2014). "In addition, it has been shown that ANGPTL3 is highly expressed in hepatocellular carcinoma, ovarian cancer, and oral squamous cell carcinoma, which may be related to the fact that ANGPTL3 induces cancer‐associated fibroblasts differentiation." (PMID 38344397, 2024). "To explore the role of ANGPTL3 in IL-1β-induced NF-κB activation, we overexpressed ANGPTL3-Flag plasmids in the human embryonic kidney cell line HEK293T and the human hepatocellular carcinoma cell line Hep3B." (PMID 37634084, 2024). "The effect of HCV on ANGPTL-3 and ANGPTL-4 gene expression during long-term infection of hepatoma cells in vitro was also studied." (PMID 34360721, 2021). "Taken together, the absence of ANGPTL3 determined lipid accumulation in human hepatoma cell line Huh7, by promoting the de novo lipogenesis independently from PCSK9, and without determining an increase in the secretion of apoB-containing lipoproteins." (PMID 38612519, 2024).
Nephropathy (15 papers, 2015 to 2024). A nonspecific term referring to disease or damage of the kidneys. "Recently, increasing evidence has suggested that ANGPTL3 is involved in the occurrence of nephropathy-associated proteinuria." (PMID 35399079, 2022). "This revelation will help to deepen the understanding of the mechanisms of glomerulosclerosis and podocyte loss, and may indicate that Angptl3 is an attractive therapeutic target in podocyte injury during the occurrence and progression of nephropathy." (PMID 31126248, 2019). "Our previous study found that the expression of Angptl3 was upregulated in nephrotic syndrome kidney tissue, and altered expression of Angptl3 in the glomerulus was associated with proteinuria and foot process effacement in kidney diseases." (PMID 25884163, 2015). "Emerging research supports a significant link between ANGPTL3 inhibition and reduced CKD risk, with several studies underscoring the protective role of ANGPTL3 inhibition in renal diseases." (PMID 39877840, 2024). "ANGPTL3 was reported as a critical molecular target for cytoskeletal rearrangement of the podocyte by the ADR-induced nephropathy." (PMID 37266537, 2023). "ANGPTL3 was closely correlated with nephropathy in vivo and in vitro, knockdown of ANGPTL3 or anti-ANGPTL3 monoclonal antibodies showed significant protective effects on rats with ADR-induced nephropathy." (PMID 37266537, 2023). "ANGPTL3 knockout not only ameliorated ADR-induced nephropathy in the early stage, but also protected it from progression." (PMID 37266537, 2023). "Subsequently, our group found that ANGPTL3 level was closely correlated with nephropathy in vivo and in vitro." (PMID 37266537, 2023). "Angptl3 is a novel factor with varying expressions and functions in different diseases; however, its role in kidney diseases has been seldomly reported." (PMID 37638046, 2023). "For the first time, we evaluated the effects of Nephropathy Prescription I on the expression of Angptl3 in nephrotic animals." (PMID 38149181, 2022). "Collectively, these data suggest that Nephropathy Prescription I exhibited protective effects against adriamycin-induced nephropathy by regulating Angptl3, nephrin, and podocin." (PMID 38149181, 2022). "Further studies found elevated mRNA levels of Angptl3 in the glomeruli of children with kidney disease compared to normal controls, and higher expression of Angptl3 in minimal change disease." (PMID 38149181, 2022). "The deletion of ANGPTL3 can reduce proteinuria in mouse models of nephropathy, and ANGPTL3 activation of integrin β3 has been identified in patients with nephrotic syndrome." (PMID 29393909, 2018). "Furthermore, its protective effects on rats with ADR-induced nephropathy were validated by knockdown of ANGPTL3 or anti-ANGPTL3 monoclonal antibodies." (PMID 37266537, 2023). "Although there are some limitations for the present study; nephropathy was not confirmed by the kidney biopsy and the cross-sectional design of the study limited us to concluding a causal relation between ANGPTL3 and renal function." (PMID 37312105, 2023). "The protective effects of the Nephropathy Prescription I may function by reducing Angptl3 expression and increasing nephrin and podocin expression." (PMID 38149181, 2022). "In our published studies, we also confirmed that ANGPTL3 can affect the expression levels of podocyte lipid raft-associated molecules such as nephrin and ACTN4 in an adriamycin-induced nephropathy model and can then aggravate the cytoskeleton rearrangement and cell motility of podocytes." (PMID 36123608, 2022). "Our preliminary work in mice with ADR-induced nephropathy observed that whole body knock out of Angptl3 or podocyte-specific Angptl3 knock out had comparable benefits in reducing proteinuria and podocyte damage in (unpublished data), corroborating the findings of this study." (PMID 36229446, 2022). "Angptl3 antagonists or inhibitors might have therapeutic potential in the occurrence and progression of nephropathy." (PMID 31126248, 2019).
Nephropathy (continued). "Interestingly for other members of the angiopoietin-like protein family such as ANGPTL3, on which betatrophin has a regulatory effect by promoting ANGPTL3 cleavage, a higher serum concentration in patients with kidney disease has been described." (PMID 28257453, 2017). "However, ANGPTL3 also has made a great progress in the field of kidney disease." (PMID 37266537, 2023). "In models of nephropathy induced by adriamycin or puromycin, as well as LPS-induced AKI, the inhibition of ANGPTL3 markedly reduces proteinuria, podocyte apoptosis, and renal functional impairment." (PMID 39840089, 2024). "In summary, other members of the ANGPTL family, including ANGPTL2, ANGPTL3, and ANGPTL8, also contribute to the regulation of inflammation, fibrosis, and metabolic disturbances in kidney diseases." (PMID 39840089, 2024). "The current study proposes that Angptl3 antagonists or inhibitors are potential and attractive therapeutic candidates for podocyte injury and proteinuria in the occurrence and progression of nephropathy, which has not been proposed in other studies." (PMID 31126248, 2019). "However, few studies have concentrated on the role of ANGPTL3 in NS, and we first discovery that ANGPTL3 was upregulated in minimal change nephrotic syndrome (MCNS) kidney tissues, which clarified the importance of ANGPTL3 in the pathogenesis of podocyte injury and nephropathy proteinuria." (PMID 37266537, 2023).
Hypertension (12 papers, 2017 to 2025). The presence of chronic increased pressure in the systemic arterial system. "Subjects with ANGPTL3 rs2131925 (T>G) T allele had more hypertension than those with the minor genotype GG." (PMID 29989339, 2018). "Men with ANGPTL3 rs2131925 (T>G) T allele had more hypertension than those with the minor genotype GG." (PMID 29989339, 2018). "For ANGPTL3 rs2131925 (T>G), men with the T allele had more hypertension than those with the minor genotype GG." (PMID 29989339, 2018). "Association of LRP1 1 rs11613352 and ANGPTL3 rs2131925 with hypertension might imply a direct effect at the artery wall." (PMID 29989339, 2018). "A potential role in hypertension for ANGPTL3 is possible, since its blood levels have been shown to be closely associated with arterial wall thickness." (PMID 29989339, 2018). "This strategy was successfully applied to find new genetic variants for Mendelian CVDs such as hypertension (KCNJ5, KLHL3 gene), dilated cardiomyopathy (BAG gene), or familial combined hypolipidemia (ANGPTL3 gene)." (PMID 29445720, 2017). "We also found an interaction between ANGPTL3 and hypertension." (PMID 38425231, 2024). "The ANGPTL3 expression level was an independent risk factor for CAD in patients with hypertension, but not in those without hypertension." (PMID 38425231, 2024). "The ANGPTL3 expression level was an independent risk factor for CAD in patients with hypertension, but not in those without hypertension (OR per 1 SD [95% CI]: 7.661 [2.278, 25.761], p = .001 vs. 1.541 [0.718, 3.311], p = .267; p for interaction = 0.030)." (PMID 38425231, 2024). "As a member of the angiopoietin-like protein family, ANGPTL3 is involved in the proliferation of vascular endothelial cells, and whether this molecule is related to hypertension needs to be investigated." (PMID 31103046, 2019). "Moreover, the results showed that ANGPTL3 and hypertension interact with each other in CAD." (PMID 38425231, 2024). "Subsequently, the independent association between FABP4, ANGPTL3 and ANGPTL4, and CAD was assessed in various subgroups according to sex (male or female) and hypertension (with or without)." (PMID 38425231, 2024). "Given the role of ANGPTL3, ANGPTL4 and ANGPTL8 in regulating lipid metabolism we hypothesised that their levels might be increased in subjects with hypertension." (PMID 29490644, 2018). "Similar to the plasma levels, ANGPTL3 expression was not different between subjects with and without hypertension (p = 0.47)." (PMID 29490644, 2018). "Similarly, in subjects with T2D, ANGPTL4 and ANGPTL8 levels (p < 0.05), but not ANGPTL3 levels, were significantly higher in subjects with hypertension." (PMID 29490644, 2018). "In this study, we measured the expression of ANGPTL3, ANGPTL4 and ANGPTL8 in both plasma and adipose tissue in subjects with and without hypertension." (PMID 29490644, 2018). "Dyslipidaemia is a risk factor for hypertension development; however, the roles of ANGPTL3, ANGPTL4 and ANGPTL8 in subjects with hypertension have not yet been established." (PMID 29490644, 2018). "This study compared the plasma and adipose tissue levels of ANGPTL3, ANGPTL4 and ANGPTL8 in age- and body mass index-matched subjects with and without hypertension." (PMID 29490644, 2018). "Therefore, we examined the plasma and adipose tissue levels of ANGPTL3, ANGPTL4 and ANGPTL8 in subjects with or without hypertension using ELISA and real-time PCR." (PMID 29490644, 2018).
homozygous familial hypercholesterolemia (10 papers, 2021 to 2026). "ASOs: antisense oligonucleotides; LDL-C: low-density lipoprotein-cholesterol; HoFH: homozygous familial hypercholesterolemia; ANGPTL3: angiopoietin-like protein 3; PCSK9: proprotein convertase subtilisin/kexin type; LFTs: liver function tests." (PMID 40264627, 2025). "The efficacy and safety of evinacumab, a fully human monoclonal antibody against ANGPTL3, was investigated in the Efficacy and Safety of Evinacumab in Patients With Homozygous Familial Hypercholesterolemia trial." (PMID 33716107, 2021). "In February 2021, Evinacumab, a monoclonal antibody against ANGPTL3 was approved by the FDA for the treatment of homozygous familial hypercholesterolemia (HoFH) as an adjunct to existing LDL cholesterol-lowering therapies." (PMID 35107764, 2022). "In 2020, the Evinacumab Lipid Studies in Patients with Homozygous Familial Hypercholesterolemia (ELIPSE HoFH) trial evaluated the efficacy of evinacumab, a monoclonal antibody against ANGPTL3, in reducing LDL-C in patients with a genetic or clinical diagnosis of HoFH." (PMID 38543075, 2024). "Evinacumab is another monoclonal antibody that pharmacologically inhibits angiopoietin-like 3 (ANGPTL3) and was recently approved by the FDA as a complementary agent to other LDL-C-lowering therapies for patients with homozygous familial hypercholesterolemia (HoFH)." (PMID 37887310, 2023).